BCL2 (BCL2 apoptosis regulator)
Diseases named in the same sentence as BCL2 in open-access papers (continued):
Sharing a sentence is not in itself a finding about the gene and the disease.
gastric tumor (16 papers, 2006 to 2024). "The expression of PTGS2 was independently associated with ACTA2 in non-cancerous tissue, explaining 38% in gene variability, and BCL2 was independently associated with ACTA2 in gastric tumors, explaining 39% in gene variability." (PMID 32630408, 2020). "A significant increase in the expression of Bcl-2 was observed 24 h.p.i with RV in gastric tumor tissue." (PMID 37186587, 2023). "Circ-CCDC66 induced CDDC resistance via miR-618 inhibition that resulted in BCL2 up regulation in gastric tumor cells." (PMID 34099061, 2021). "Collectively, these results indicated that hsa-miR-376c-3p expression regulated the gastric tumor cell growth in vitro through BAD/BCL-2 pathway." (PMID 27965982, 2016). "An increase in the level of the Bax protein and a decrease in the level of the Bcl-2 protein (in direct proportion to the increase in resveratrol concentration 50, 200 and 400 μM) were also demonstrated in the gastric tumor cell line SGC-7901 after 24 h of incubation." (PMID 34770968, 2021). "MiR-136 and miR-449a also increased CDDP sensitivity of gastric tumor cells through BCL2 targeting." (PMID 34099061, 2021). "The expression of ACTA2, HIF1A, and VEGFA was independently associated with TJP1 in non-cancerous tissue, explaining 90% in its variability, and BCL2, HIF1A, CDKN1A, and PTGS2 were independently associated with TJP1 in gastric tumors, explaining 98% in gene variability." (PMID 32630408, 2020). "Another investigation has demonstrated that silence of the expression of Stat3 suppresses the proliferation of gastric tumors, and induces cell apoptosis and cell cycle shift induction both in vivo and in vitro significantly by regulating downstream protein Cyclin-D1, Survivin, and Bcl-2." (PMID 38238515, 2024). "The expression of PTGS2, BCL2, and IL7 (inversely) was independently associated with CCL2 in non-cancerous tissue, explaining 88% in gene variability, and HIF1A and BCL2 were independently associated with CCL2 in gastric tumors, explaining 83% in its variation." (PMID 32630408, 2020). "In conclusion, the knowledge gained from our study is that HDAC inhibitors impede gastric tumor cell migration, proliferation, and suppression of other cellular functions of tumors by regulating E2F5 through direct BCL2 targeting." (PMID 34947956, 2021). "As compared to EC, in which expression of 12 genes was altered, gastric tumors had significantly upregulated expression of only two (Ki67 and CLDN2) and downregulated one (BCL2)." (PMID 32630408, 2020).
infertile (16 papers, 2020 to 2026). "Remarkably, administration of 10-HDA and/or ZnO-NPs to PbAc-intoxified rats exhibited a significant decline (p < 0.05) in the Bax/Bcl-2 ratio compared to PbAc-infertility rats." (PMID 39349706, 2025). "In infertile males, there are higher Bcl2 mRNA levels, which indicate an attempt to prevent germ cell death." (PMID 41009773, 2025). "The deletion of Rarα resulted in 25.0% of females infertility due to vaginal closure, in which the mRNA (Ctnnb1, Bak and Bax) and protein (Cleaved Caspase-3) levels were significantly decreased, and Bcl2 mRNA levels were significantly increased in the vaginas." (PMID 37041518, 2023). "High levels of BCL2 protein in male germ cells result in highly abnormal adult spermatogenesis with infertility." (PMID 36330159, 2022). "The early wave of apoptosis removed in transgenic mice with overexpressing Bcl-2 or Bclx results in the cumulation of spermatogonia and spermatocytes, further resulting in infertile animals." (PMID 34401644, 2021). "Also, the BAX/BCL-2 ratio of sperm in infertile men increased significantly compared to fertile men." (PMID 39205917, 2024). "Accordingly, an increase in the proportion of spermatozoa with fragmented DNA correlated with an elevated BAX/Bcl-2 ratio in semen obtained following longer ejaculatory abstinence with more uropathogenic bacteria, which has also been reported in infertile men suffering from urogenital infections." (PMID 36834909, 2023). "Prevention of apoptosis is also one of the mechanisms through which LC might have demonstrated anti-infertility effect against toxicants through modulation of proapoptotic and antiapoptotic genes, such as Bcl-2, BAX, and Caspase-3." (PMID 35814917, 2022). "BCL-2 has multiple cell proliferation disorders, other immunodeficiency and infertility." (PMID 36518133, 2022). "Network pharmacology identified linoleic acid, oleic acid, biotin, and esculentic acid as key contributors to the extract's anti-infertility effects, potentially via interactions with EGFR, HIF1, BCL2, TNF, and AKT1." (PMID 42199843, 2026). "An abrogated initial wave of apoptosis in transgenic mice overexpressing BCL-2 or BCL-x leads to accumulation of spermatogonia and spermatocytes, resulting in infertile animals." (PMID 39205917, 2024). "Studies confirmed that infertile men showed a significant BAX increase and BCL2 decrease in seminal fluid at both mRNA and protein levels; moreover, the mature SPZ from infertile patients with increased ROS levels had significantly higher levels of apoptosis than mature SPZ from the control group." (PMID 40710375, 2025). "Also, the mechanism of control over the rate of gene transcription or transcriptional regulation is altered in genes involved in chronic endometritis and the inflammatory response (IL-11, CCL4), growth factors (IGFBP1), and apoptotic proteins (BCL2, BAX, CASP8) in infertile patients." (PMID 33329514, 2020).
invasive breast carcinoma (16 papers, 1995 to 2024). A carcinoma that infiltrates the breast parenchyma. "In this model, Bcl-2 positivity of feline invasive mammary carcinomas was associated with a 2-fold decrease in the risk of cancer-related death (HR = 0.50, 95%-CI: 0.30–0.84; p = 0.008)." (PMID 30630524, 2019). "The expression of BCL-2, an apoptotic cell death suppressor, was studied in 52 invasive breast carcinomas." (PMID 36243702, 2022). "THSWD combined with chemotherapy drugs in the treatment of invasive breast cancer can promote tumor cell apoptosis by down-regulating Bcl-2 protein, up-regulating Bax protein, and reducing Bcl-2/Bax ratio." (PMID 34857023, 2021). "The aim of our study was to determine the frequency of Bcl-2 expression in feline invasive mammary carcinomas (FMCs), its relationship with other clinicopathologic variables, and its prognostic value." (PMID 30630524, 2019). "Accordingly, BCL2 and E-cadherin were evaluated in a series of n = 172 human primary invasive breast cancers compiled on TMAs using immunohistochemical stainings." (PMID 24023670, 2013). "We found differences between the frequency of expression of ERα (88%) and ERβ (36%) (p = 0.007); bcl-2 was expressed in 79.5% of invasive breast carcinomas." (PMID 16911782, 2006). "Differences were found between the expression of ERα 39 (88%) and ERβ 16 (36%) (p = 0.007); the expression of bcl-2 was seen in 35 (79.5%) invasive breast carcinomas." (PMID 16911782, 2006). "The probability of cancer-related death in this cohort of female cats with invasive mammary carcinoma could be predicted with Bcl-2 expression and the 3 parameters of cancer stage (tumor size, nodal stage, and distant metastasis)." (PMID 30630524, 2019). "It is also of note that Bcl-2 has recently been reported as a powerful independent predictor of good prognosis in a study of >11 000 invasive breast carcinomas, and this further suggests that the clustering of DCIS into subgroups defined in part by Bcl-2 may be of functional and clinical importance." (PMID 21139586, 2011). "Furthermore, immunostaining revealed that most of the patients with invasive breast carcinoma (IBC) strongly expressed Ki-67 (Ki-67+) and BCL-2 (BCL-2+), with proportions of 85.5% (65/76) and 57.9% (44/76) respectively." (PMID 31289309, 2019).
Myocardial fibrosis (16 papers, 2012 to 2025). "BCL2 is an anti-apoptotic protein for heart fibroblast and is reported to be potentially associated with myocardial fibrosis phenotype in patients with dilated cardiomyopathy (DCM)." (PMID 32244749, 2020). "Following treatment with Urantide, we found that DOX-induced myocardial fibrosis and apoptosis were greatly improved, and the expression levels of apoptosis-related proteins were significantly affected, with upregulation of Bcl-2 and downregulation of Bax." (PMID 36690700, 2023). "The results of this study indicate that MSC transplantation can attenuate myocardial fibrosis and increase Bcl-2 expression levels following DOX injection." (PMID 23508361, 2012). "We conclude that intravenous transplantation of MSCs and CM can attenuate myocardial fibrosis and increase Bcl-2 expression." (PMID 23508361, 2012). "Therefore, our results indicate that lower LAT1 can improve mitochondrial dysfunction and relieve apoptosis and myocardial fibrosis via the mTOR/Bax/Bcl-2/caspase-3 signaling pathway, and there was a positive feedback loop between LAT1 and mTOR." (PMID 39182099, 2024). "QL:reducte in myocardial fibrosis, promote TGF-β3/Smad7, and inhibite TGF-β1/Smad3;reverse Bax/Bcl-2 upregulation;inhibite Smad3 by upregulating miR-345-3p." (PMID 40881586, 2025). "The ultrastructure, degree of myocardial fibrosis, apoptosis index (AI), expression of microRNA-1, expression of microRNA-21, and mRNA of TIMP-1, MMP-9, BCL-2, and Bax of patients were compared and analyzed in each group." (PMID 34957910, 2021). "Metabolic characteristics, cardiac function and morphology, myocardial remodeling, myocardial fibrosis (collagen III, α-SMA, and TGF-β), oxidative stress (NRF2, HO-1, SOD, and NOX4), and apoptosis (BAX, Bak, Bcl-2, and Bcl-XL) were analyzed 24 weeks after the different treatments." (PMID 34520392, 2021). "Furthermore, YQWY decoction markedly inhibited MTAC-induced myocardial fibrosis as evidenced by downregulated collagen I, TGF-β, and CTGF in myocardium and alleviated apoptosis (downregulated caspase-3 and PARP and increased Bcl-2/Bax ratio in cardiomyocytes)." (PMID 33456490, 2020). "SPD treatment also decreased the ratio of BAX to BCL2 expression and percentage of TUNEL-positive nuclei as well as inhibited myocardial fibrosis (collagen deposition) within the myocardium of IUH-exposed neonates, reversing the effects seen under hypoxia exposure." (PMID 31217839, 2019).
Nephropathy (16 papers, 2016 to 2025). A nonspecific term referring to disease or damage of the kidneys. "Bax expression is increased and Bcl-2 expression is decreased as a result of DOX-induced kidney damage, which causes apoptosis." (PMID 37841924, 2023). "Bcl-2 is linked to kidney disease through the processes of apoptosis and fibrosis." (PMID 36699321, 2022). "Diabetic patients with poor glycemic control exhibit the downregulation of BCL2, which activates the NF-kB pathway, thus leading to the development of nephropathy." (PMID 36094934, 2022). "Forty patients with renal diseases possessed lower Bcl-2 gene expression in their blood samples than in 20 healthy individuals." (PMID 36699321, 2022). "Among these targets, Bcl-2, a critical apoptosis-related protein in kidney disease, showed a high score of 0.9933 and appeared at a higher frequency, as shown in the mapping." (PMID 34253875, 2022). "We evaluated the renal cell death by focusing on the RNA expression of apoptosis indicators Bcl-2, Caspase-9, and biomarkers of nephropathy (NGAL, KIM-1)." (PMID 33933022, 2021). "Overall, our findings demonstrated that ZIKV infection induced AKI by activating NLRP3 inflammasome and apoptosis through suppressing Bcl-2 expression, which provided potential therapeutic targets for ZIKV-associated renal diseases." (PMID 31474993, 2019). "Overall, our findings uncovered a link between ZIKV and kidney disease and identified Bcl-2 as a potential target in the intervention of ZIKV-induced AKI." (PMID 31474993, 2019). "The expression levels of Cleaved‐Caspase3 and Bax were significantly increased, and Bcl‐2 levels were decreased, in adriamycin‐induced nephropathy rats, while PA and EPI could decrease the levels of Cleaved‐Caspase3 and Bax and increase the levels of Bcl‐2." (PMID 37382268, 2023). "In kidney diseases, it was noted that Bcl-2 may be downregulated with subsequent enhancement in a Bax-induced apoptotic effect." (PMID 33212804, 2020). "In another model of kidney damage, mitochondrial transplantation (MT) also promoted SOD and ATP levels while reducing apoptosis by increasing Bcl-2 expression." (PMID 40741287, 2025). "Resveratrol, with the property of reducing oxidative stress-mediated renal injury in the animal model of nephropathy, can inhibit PTH induced apoptosis and restore bcl-2 expression as a sirtuin 1 agonist." (PMID 35166167, 2022). "Thus, Bcl-2 may be related to kidney disease through apoptosis." (PMID 36699321, 2022). "In order to analyze the principal component analysis (PCA), factors that interacted with CKD progression (such as circulating Bcl-2, blood urea nitrogen (BUN), creatinine, and kidney disease stage) were examined." (PMID 36699321, 2022). "Our results showed that SCSP treatment significantly upregulated the expression level of apoptotic protein Bcl-2 (p < 0.01) and downregulated Bax, TNF-α, and caspases 3 and 9, thereby reversing the CTX-induced kidney damage." (PMID 32916975, 2020). "Consistent with our findings, CHOP deficiency effectively ameliorates renal cell apoptosis via the inhibition of Bcl-2 down-regulation and JNK activation during obstruction-induced nephropathy." (PMID 26942460, 2016). "More importantly, our study identified Bcl-2 as a negative regulator of ZIKV-induced NLRP3 inflammasome activation and renal cell apoptosis, which provided a new insight of the therapeutic target for renal diseases induced by viral infection." (PMID 31474993, 2019). "These proteins are inhibited by pro-survival Bcl-2 proteins and many studies have demonstrated that BAX and BAK proteins participate in apoptotic/necrotic process in kidney disease and the silencing of their functions could prevent apoptosis and the subsequent fibrogenic signaling." (PMID 37760081, 2023).
Nephropathy (continued). "In renal disease, multiple stimuli may lead to the synthesis of reactive oxygen species, among which nicotinamide adenine dinucleotide phosphate (NADPH)-induced oxidative stress upregulates the expression of apoptosis regulator Bax proteins and downregulates apoptosis regulator Bcl-2 content." (PMID 35295738, 2021).
acute promyelocytic leukemia (15 papers, 2011 to 2025). An aggressive form of acute myeloid leukemia (AML), characterized by arrest of leukocyte differentiation at the promyelocyte stage, due to a specific chromosomal translocation t(15;17) in myeloid cells. "The present findings are supported by several studies that demonstrated reduced expression of Bcl-2 proteins in HepG2 (human hepatocyte carcinoma) and HL-60 (human promyelocytic leukemia) cells when treated with LAAO." (PMID 29890640, 2018). "Previously, Wang and colleagues in 2002 demonstrated 6-gingerol effects on apoptosis induction and inhibition of Bcl-2 expression in promyelocytic leukemia HL-60 cell." (PMID 28761826, 2017). "Co-immunoprecipitation of SLIRP with endogenous bcl-2 was observed in other cell lines, such as acute promyelocytic leukemia HL60 and human epithelial cervix adenocarcinoma HeLa cells." (PMID 26866271, 2016). "In contrast, for the HL-60 human promyelocytic leukemia cell line, onconase induced the expression of Bax while decreasing that of Bcl-2." (PMID 21223552, 2011). "In contrast to these studies of NE-regulated suppression of cancer, ELANE is expressed in promyelocytic leukemia (PML) and sustains PML by inhibiting apoptosis via degradation of BAX a pro-apoptotic protein and upregulation of Bcl-2, an apoptosis inhibitor." (PMID 39684750, 2024).
cardiomyopathy (15 papers, 2012 to 2025). A disease of the heart muscle or myocardium proper. "Our results clarified that TIL caused upregulation of caspase-3, Bax and downregulation of Bcl-2 expression, which reflects the apoptotic role in TIL-induced cardiomyopathy." (PMID 37888707, 2023). "In fact, increased expression of anti-apoptotic proteins in cardiomyocytes, such as Bcl-2, and increased apoptosis in general is a consistent feature of end-stage heart failure and correlates with the clinical severity of cardiomyopathy." (PMID 34068392, 2021). "To investigate the anti-apoptotic effects of MSC-sEVs on myocardium in the DOX-induced cardiomyopathy model, we evaluated the expression levels of survivin and Bcl-2 in the heart tissues of mice." (PMID 34281156, 2021). "As expected, our present study has demonstrated that anti-apoptotic protein Bcl-2 was decreased, pro-apoptotic protein Bax was increased, and cleaved caspase 3 protein, reflective of caspase activity, a marker of apoptosis, was increased in doxorubicin cardiomyopathy." (PMID 38521855, 2024). "BCL2/adenovirus E1B 19 kDa protein-interacting protein 3-like (BNIP3L) activates the ER and mitochondrial cell death pathways and induces cardiomyopathy." (PMID 39457090, 2024). "Our study revealed that the abundance of Bax and Bcl2 were significantly changed in the MI model and restored in XML pretreated cardiomyopathy." (PMID 35141226, 2022). "Herein, the immunohistochemical staining of myocardial tissues showed that DOX caused an increase in the cleaved caspase-3 and Bax expressions and decreased Bcl-2 expression, which reflected apoptosis’s role in DOX-induced cardiomyopathy." (PMID 33804672, 2021). "In vitro treatment of PBMCs with IL-27 and IL-7 improved monofunctional and polyfunctional Th1 responses, accompanied by the induction of IL-10 and Bcl-2 expression in subjects without heart disease but did not improve those in subjects with cardiomyopathy." (PMID 34061845, 2021).